HRG (histidine rich glycoprotein)
Diseases named in the same sentence as HRG in open-access papers (continued):
Sharing a sentence is not in itself a finding about the gene and the disease.
ischemic stroke (3 papers, 2020 to 2022). A stroke disorder caused by obstruction of blood flow to the brain, due to thrombotic (local blood clot formation) or embolic (due to a blood clot or other material traveling from another site) event. "A2MG, C1QB, C1R, and HRG were found to be potential predictors of ischemic stroke development; however, further validation and investigation are necessary to determine the roles of all of these differentially expressed proteins in ischemic stroke development." (PMID 34912031, 2021). "We revealed marked upregulation of four proteins (A2MG, C1QB, C1R, and HRG) in EVs enriched fractions by 7.3 ± 4.4 years before ischemic stroke onset, indicating their potential as biomarkers for predicting future ischemic stroke events." (PMID 34912031, 2021). "In comparison to age- and sex-matched controls who did not develop any brain lesion, alpha-2-macroglobulin (A2MG), complement C1q subcomponent subunit B (C1QB), complement C1r subcomponent (C1R), and histidine-rich glycoprotein (HRG) were significantly upregulated in the ischemic stroke patients." (PMID 36140248, 2022). "Alpha-2-macroglobulin (A2MG), complement C1q subcomponent subunit B (C1QB), complement C1r subcomponent (C1R), and histidine-rich glycoprotein (HRG) were significantly upregulated by 2.21-, 2.15-, 2.24-, and 2.16-fold, respectively, in the ischemic stroke group as compared to the control group." (PMID 34912031, 2021). "Our study also demonstrated that HRG was highly expressed in ischemic stroke patients." (PMID 32466277, 2020).
thrombosis (3 papers, 2016 to 2024). "In animal models, HRG deficiency has been reported to enhance thrombin generation and promote arterial thrombosis." (PMID 32076463, 2020). "The univariate GWAS confirmed that SNP rs9898 is associated with Histidine Rich Glycoprotein (HRG) levels, but previous results also reported that it was associated with Activated Prothrombin Time (aPTT) trait and consequently with thrombosis risk." (PMID 28005926, 2016). "Accordingly, when labeled with fluorophore and infused into Hrg−/− mice, gof-HRG showed increased accumulation at the site of vessel injury in the laser-induced thrombosis model." (PMID 38605050, 2024). "Using the laser injury-induced thrombosis model, we visualized the assembly of platelets and HRG using Dylight-649-conjugated anti-CD42c and Alexa-488-conjugated anti-HRG, respectively." (PMID 38605050, 2024). "Notably, in the FeCl3-induced thrombosis model, which is mediated in part by FXIIa22, the antithrombotic activity of FXIIa-bound HRG22 may counter-balance the prothrombotic activity of endothelial-bound HRG via its neutralization of HS11,24,40,41." (PMID 38605050, 2024).
gastric cancer (2 papers, 2016 to 2017). A primary or metastatic malignant neoplasm involving the stomach. "In summary, this is the first report showing that APIP displays a pivotal oncogenic activity by binding to ERBB3 to stimulate the formation of ERBB3/ERBB2 heterodimer, leading to amplification of HRG-mediated signaling involved in cell proliferation and tumorigenesis in gastric cancer." (PMID 26942872, 2016).
glioblastoma (2 papers, 2009 to 2012). The most malignant astrocytic tumor (WHO grade IV). "We found that HRG could significantly inhibit the development of malignant tumors and prevent development of glioblastoma." (PMID 20046875, 2009).
liver disease (2 papers, 2020 to 2023). "Previous studies have found that HRG plays an important role in liver disease by regulating macrophage polarisation, while the effect of HRG on tumour metastasis has not been studied." (PMID 37254661, 2023). "In some studies, HRG deficient mice are protected from liver injury and liver fibrosis, which are two prerequisites for the occurrence of HCC in human liver diseases." (PMID 32210020, 2020).
Miscarriage (2 papers, 2018 to 2022). A pregnancy that ends at a stage in which the fetus is incapable of surviving on its own, defined as the spontaneous loss of a fetus before the 22th week of pregnancy. "Furthermore, specific HRG polymorphisms have been associated with recurrent miscarriage and infertility with the possible hypothesis that the amino acid substitution induces a conformational change on the HRG protein which affects its function." (PMID 29540166, 2018). "Moreover, analysis using ROC curves showed that the expression level of HRG in patients undergoing IVF/ICSI cycles may provide a candidate biomarker to predict reproductive outcomes (e.g., live birth versus not pregnant or miscarriage) in such patients." (PMID 36528562, 2022).
ovarian carcinoma (2 papers, 2010 to 2017). A malignant neoplasm originating from the surface ovarian epithelium. "In contrast, they reported elevated levels of a number of proteins (e.g., hemopexin, histidine-rich glycoprotein, and vitronectin) that were identified in our study but did not meet our criteria for overexpression in ovarian cancer serum." (PMID 20546617, 2010).
ovarian tumours (2 papers, 2009 to 2018). "When CD44-siRNAs are delivered to ovarian tumours it down regulates CD44 resulting in prevention of HRG-mediated ovarian tumour cell growth and decreased migration." (PMID 29510526, 2018). "The correlation of HRG/NRG1 and ITGB3 expression might be relevant to study in ovarian tumours as well, or there might be other unknown factors that regulate the impact of ITGB3 as a biomarker." (PMID 19775429, 2009).
preeclampsia (2 papers, 2022 to 2024). Preeclampsia is a hypertensive disorder of pregnancy that is characterized by new-onset hypertension with proteinuria presenting after 20 weeks of gestation, and depending on mild or severe forms may initially present with severe headache, visual disturbances, and hyperreflexia. "HRG is known to be an important protein in early pregnancy, and former studies have revealed the existence of a positive relationship between HRG in the placenta and the risk of preeclampsia during pregnancy." (PMID 38659607, 2024).
rheumatoid arthritis (2 papers, 2020 to 2022). A chronic, systemic autoimmune disorder characterized by inflammation in the synovial membranes and articular surfaces. "Furthermore, a recent work establishes a correlation between low levels of histidine-rich glycoprotein (HRG), a glycoprotein with a high concentration of histidine; and high levels of RF, which suggests the use of HRG as a biomarker for rheumatoid arthritis." (PMID 33158306, 2020).
Stroke (2 papers, 2020 to 2021). Sudden impairment of blood flow to a part of the brain due to occlusion or rupture of an artery to the brain. "Moreover, platelets are reportedly activated during stroke while HRG binds to the activated platelets surface." (PMID 32466277, 2020).
adenoma (1 paper, 2014). A neoplasm arising from the epithelium. "Blinded scoring demonstrated strong or moderate stromal immunostaining for HRG in the majority of normal (healthy) and adenoma tissues." (PMID 25243896, 2014).
AIDS (1 paper, 2013). A syndrome resulting from the acquired deficiency of cellular immunity caused by the human immunodeficiency virus (HIV). "Levels of plasma histidine-rich glycoprotein have been found to decrease during acute states of disease such as advanced liver cirrhosis, AIDS, renal disease, asthma, and pulmonary disease." (PMID 23762862, 2013).
antiphospholipid syndrome (1 paper, 2008). A disorder caused by the presence of autoantibodies directed against phospholipids, causing a hypercoaguable state, which may result in blood clots, stroke, heart attack, and in women, significant pregnancy-related complications, including miscarriage and still birth. "In this context, it is particularly interesting that antibodies against HRG have been detected in patients with antiphospholipid syndrome, a disease associated with thrombodiathesis and systemic lupus erythematosus." (PMID 18797515, 2008).
Arthritis (1 paper, 2024). Inflammation of a joint. "While histidine-rich glycoprotein (HRG) has been identified as a biomarker in adult RA, acetate has not previously been linked to arthritis." (PMID 39736759, 2024).
B‐cell lymphomas (1 paper, 2020). "The expression and role of HRG in human B‐cell lymphomas was investigated in order to find new tools for prognosis and treatment." (PMID 35847718, 2020). "In conclusion, HRG protein is present in several mature B‐cell lymphoma types with MZL having the highest proportion of HRG‐positive patients." (PMID 35847718, 2020). "Here, we show that HRG is expressed in several mature B‐cell lymphomas." (PMID 35847718, 2020). "Here, we present for the first time evidence that HRG is expressed by tumor cells in MZL and is present to variable degrees in several other human mature B‐cell lymphoma types including FL, MCL, and DLBCL." (PMID 35847718, 2020). "Mature B‐cell lymphoma TMAs including MZL (n = 59), FL (n = 51), MCL (n = 31), DLBCL (n = 139), and PCNSL (n = 33) were immunostained for the presence of HRG in the tumor compartment." (PMID 35847718, 2020).
Candida infection (1 paper, 2008). "To investigate the role of HRG during Candida infection in vivo, we designed a mouse model of intraperitoneal infection with C. albicans." (PMID 18797515, 2008).
cardiomyopathy (1 paper, 2021). A disease of the heart muscle or myocardium proper. "Other studies focusing on a Han population found an association between a prognosis of heterogeneous cardiomyopathy with SNPs associated with LGALS3, AGCT, SLC25A13, HRG, APOB, SOD3, SYNM, and TLN2." (PMID 34572079, 2021).
cervical cancer (1 paper, 2025). A primary or metastatic malignant neoplasm involving the cervix. "Eventually, we obtained a seven-mRNA–lncRNA gene cluster (four mRNAs: ART3, HRG, MAPT, and SYTL5; three lncRNAs: AC011239.1, AC125616.1, and RUVBL1.AS1) that was mostly relevant to LNM of cervical cancer." (PMID 40444278, 2025). "Among these transcripts, AC125616.1, HRG, MAPT, RUVBL1.AS1, and SYTL5 were found to be upregulated, while AC011239.1 and ART3 were downregulated in cervical cancer patients with LNM compared to those without it." (PMID 40444278, 2025).
Cholecystitis (1 paper, 2025). The presence of inflammatory changes in the gallbladder. "Notably, we identified a subset of eight plasma proteins (PAHX, CD8A, HRG, CRIS2, Dynactin subunit 2, AT2A3, CSTN2, and DEPP) that effectively differentiated GBC from cholecystitis with a diagnostic accuracy of 94% when validated on a test set." (PMID 40470116, 2025).
Cirrhosis (1 paper, 2013). A chronic disorder of the liver in which liver tissue becomes scarred and is partially replaced by regenerative nodules and fibrotic tissue resulting in loss of liver function. "Complement C3, ceruloplasmin, histidine rich glycoprotein (HRG), CD14 and hepatocyte growth factor (HGF), as validated by western blot, were considered putative biomarkers in differentiating early HCC from cirrhosis with a sensitivity of 72% and a specificity of 79%." (PMID 23401773, 2013).
cyst (1 paper, 2016). A sac-like closed membranous structure that may be empty or contain fluid or amorphous material. "To prove that HRG signaling was disrupting apical-basolateral polarity and not simply inducing hyperproliferation leading to luminal filling, we analyzed cyst development in more detail." (PMID 27447549, 2016).
esophageal cancer (1 paper, 2026). A primary or metastatic malignant neoplasm involving the esophagus. "In esophageal cancer, ANXA10 was remarkably down-regulated, and HRG was up-regulated." (PMID 41924732, 2026).
follicular lymphoma (1 paper, 2020). Follicular lymphoma is a form of non-Hodgkin lymphoma characterized by a proliferation of B cells whose nodular structure of follicular architecture is preserved. "Expression was also detected in follicular lymphoma (22%), mantle cell lymphoma (19%), and indiffuse large B‐cell lymphoma (DLBCL;5%) while primary CNS lymphoma (PCNSL) lacked expression of HRG." (PMID 35847718, 2020).
hemorrhage (1 paper, 2021). Loss of blood from the vascular compartment to the exterior or into nonvascular body space as a result of rupture or severance of the blood vessels. "Thus, the cleavage of histidine-rich glycoprotein by HF3 would have a variety of implications in the context of hemorrhage, mostly related to its role in regulating hemostasis." (PMID 34822548, 2021).
hyperglycaemia (1 paper, 2023). "Likewise, the differences observed for GPX3 and HRG could stem from the challenges created by hyperglycaemia." (PMID 37537394, 2023).
insulinoma (1 paper, 2011). "In agreement, platelet levels were significantly reduced in blood from wild type mice with insulinoma (RT2/HRG+/+) compared to healthy wild types (HRG+/+)." (PMID 21264222, 2011). "Lack of HRG enhances the angiogenic switch and, as demonstrated here, growth of insulinoma in the RIP1-Tag2 mouse." (PMID 21264222, 2011). "With the aim to investigate how lack of HRG affects tumor angiogenesis and growth in vivo, we crossed HRG-deficient mice with the RIP1-Tag2 model of spontaneous insulinoma." (PMID 21264222, 2011).
intrahepatic cholangiocarcinoma (1 paper, 2020). A carcinoma that arises from the intrahepatic bile duct epithelium in any site of the intrahepatic biliary tree. "Another gene, HRG, was significantly deregulated in intrahepatic cholangiocarcinoma and may inhibit tumor growth and metastasis." (PMID 32040444, 2020).
intrauterine growth restriction (1 paper, 2025). "In addition, lower urinary levels of histidine-rich glycoprotein (HRG) and kallikrein-1 (KLK1) suggest impaired angiogenesis and kallikrein–kinin signaling, processes implicated in pre-eclampsia and intrauterine growth restriction." (PMID 41614738, 2025).
lymphoma (1 paper, 2020). A malignant (clonal) proliferation of B- lymphocytes or T- lymphocytes which involves the lymph nodes, bone marrow and/or extranodal sites. "In MZL, HRG expression in tumor cells was detected in more than a third of samples, while the prevalence in the other lymphoma cohorts analyzed was lower." (PMID 35847718, 2020). "We therefore examined the expression and potential role for HRG in human lymphomas." (PMID 35847718, 2020). "Indolent, low‐grade lymphomas like MZL and FL more frequently expressed HRG, whereas high‐grade lymphomas like DLBCL and PCNSL showed low or no expression." (PMID 35847718, 2020).
marginal zone lymphoma (1 paper, 2020). A usually indolent mature B-cell lymphoma, arising from the marginal zone of lymphoid tissues. "Immunohistochemical (IHC) analysis and RNA hybridization of tissue microarrays showed that (i) HRG was expressed by tumor cells in marginal zone lymphoma (MZL), in 36% of 59 cases." (PMID 35847718, 2020).
mastitis (1 paper, 2016). Inflammation of breast tissue during lactation or postpartum due to an obstructed duct or infection. "Proteins that have not been previously associated with mastitis, including HRG, an acute-phase and antimicrobial protein, have been quantified." (PMID 27412694, 2016).
monocytic leukemia (1 paper, 2017). "HRG was shown to facilitate necrotic cell clearance by phagocytes through preferential binding to HS on THP-1 cells (a human macrophage-like monocytic leukemia cell line), as supported by the cleavage of HS leading to reduced binding of HRGP (co-purified IgG with HRG) to THP-1 cells." (PMID 28257077, 2017).
oropharyngeal tumours (1 paper, 2025). "Another study applied disease pathways analysis and found that the proteins Thbs1 (or TSP-1), KNG1, Histidine-rich glycoprotein (HRG), and F9, F10, and F12 were upregulated in HPV+ variant P16-induced oropharyngeal tumours compared to non-P16 variant HPV+ tumours." (PMID 41462954, 2025).
skin melanoma (1 paper, 2022). "When we knocked down HRG in mice bearing skin melanoma, metastasis to both the brain and lungs was significantly enhanced." (PMID 36142212, 2022).
virus infection (1 paper, 2022). "In particular, vWF, HRG, PROS1, GC, F2, FGA, and FGB proteins, which are responsible for the expansion of vessels and new vessel formation, modulate blood coagulation and mitigate against vasoconstriction and coagulation caused by virus infection." (PMID 35401544, 2022).